FMR1 (fragile X messenger ribonucleoprotein 1)
Diseases named in the same sentence as FMR1 in open-access papers (continued):
Sharing a sentence is not in itself a finding about the gene and the disease.
Infertility (continued). "The mechanism for FMR1 upregulation in PM carriers is not well understood, and only correlative evidence for an increase in the binding of epigenetic marks at the FMR1 gene promoter has been found, as in the case of H3K9ac and H3K9me2 in PM infertile women." (PMID 34445074, 2021). "Another study claims that normal FMR1 repeat length outside 26 > CGG > 34 concur with a higher XCI skew, a putative mechanism underlying the ovarian reserve impairment (as assessed by AMH), particularly in infertile older females." (PMID 33281866, 2020). "We, therefore, in this study aimed to investigate whether relative expression of FMR1 RNA (and its isoforms) differ in infertile women with various ranges of CGGn (defined as 6 sub-genotypes)." (PMID 30576349, 2018). "This study also reaffirms the rapidly evolving importance of FMR1 in infertility." (PMID 21526209, 2011). "FMR1 genotype differences could represent possible explanations for observed differences in infertility treatment outcomes." (PMID 21526209, 2011). "Clearly, it is still an outstanding question whether or not the FMR1 gene is associated with low ovarian reserve and infertility, and if it is, which repeat length confers the greatest risk." (PMID 25071825, 2014). "The American College of Medical Genetics and the American College of Obstetrics and Gynecology guidelines in 2010 recommended the evaluation of women with infertility and/or elevated FSH for the FMR1 premutation based on the phenotype in known carriers." (PMID 39202368, 2024). "We evaluated the FMR1 allelic score and the X-chromosome inactivation (XCI) pattern in cohorts of infertile females and oocyte donors." (PMID 33530161, 2021). "Research on the FMR1 gene has extended to other endpoints of relevance in the OB/GYN setting for women, including infertility and ovarian hormones." (PMID 25071825, 2014). "Indeed, terminal deletions at Xq were reported as part of a workup for infertility or POI and also in women screening for FMR1 premutation." (PMID 32194616, 2020). "sXCI was significantly lower among infertility patients with norm FMR1 (6.5 ± 11.1, median and IQR) compared to those with not-norm FMR1 (12.0 ± 14.6, P = 0.005), though among young oocyte donors the opposite effect was observed." (PMID 28454580, 2017). "This study demonstrates that in consecutive patients presenting for infertility treatments the prevalence of autoimmunity varies significantly with FMR1 genotype, with het-norm/low presenting with most and het-norm/high with least autoimmunity." (PMID 21179569, 2010). "The association between FMR1 allele and infertility has been preliminarily explored in the European and American population, however, the relationship between the pattern of AGG interruptions and infertility, especially in Asian population, has not yet been elucidated." (PMID 40600017, 2025). "Changes in RNA level and/or ratio of various isoforms of the FMR1 gene may regulate, either through epigenetic processes or via the translation and cellular localization of FMRP the expression of steroidogenic enzymes and hormonal receptors, leading to ovarian dysfunction and possible infertility." (PMID 30576349, 2018). "His daughter had a history of premature menopause and infertility, suggesting FXPOI, although screening for FMR1 premutation was not available." (PMID 34498198, 2022).
epilepsy (26 papers, 2011 to 2025). A brain disorder characterized by episodes of abnormally increased neuronal discharge resulting in transient episodes of sensory or motor neurological dysfunction, or psychic dysfunction. "This is consistent with the high incidence of seizures reported in FXS patients, and in the Fmr1 KO mice, supporting a key role for dysfunction of the Kir4.1 channel in mechanisms associated with epilepsy." (PMID 38678030, 2024). "It has now become a rather common practice to derive AE models by the knockout of genes, presumably associated with epilepsy—they are Lgi1 mice, Fmr1 strain, etc.." (PMID 36428502, 2022). "Gene expression could be also affected by the methylation status of gene promoters, as was demonstrated for epilepsy-associated genes FMR1 and BRD2 (bromodomain-containing transcriptional activator 2) in humans." (PMID 36428502, 2022). "The anti‐seizure effect of E2730 against multiple seizure types was further investigated in other epilepsy animal models, such as 6 Hz‐44 mA psychomotor seizures in mice, amygdala kindling rats, Fmr1 KO mice, and Scn1a+/− mice." (PMID 37052238, 2023). "Most importantly, single-gene disorders characterized by ASD–epilepsy comorbidity (such as FMR1-, TSC1/2-, and SHANK3-mediated Phelan-McDermid syndromes) are caused by mutations in genes that regulate glutamate receptor-mediated signaling mechanisms." (PMID 36142719, 2022). "The alterations in sIPSC properties observed in Fmr1 KO mice resemble those seen in previous studies with ethanol exposed mice and a mouse model of epilepsy where the α4 subunit integrates with synaptic GABAARs." (PMID 30804752, 2019). "We found proteins from this network were also enriched in multiple mouse models (Fmr1-/y, 22q11.2+/-, Cul3-/-), and the level of enrichment in these models was consistently higher for the epilepsy network than for the global proteome disrupted in 16p11.2dup/+ mice." (PMID 36808153, 2023). "The majority of reported FMR1 CNVs were deletions identified in patients who underwent clinical testing for neurological features such as DD, ID, ASD, and/or epilepsy, with four small duplications only containing FMR1." (PMID 34828275, 2021). "This evidence is in line with several studies carried out in several experimental models of ASD-epilepsy (Cntnap2, En2, Fmr1, Nrp2), in which defects of GABAA receptor-mediated neurotransmission have been related to the pathogenesis of ASD-epilepsy comorbidity." (PMID 37153775, 2023). "Furthermore, epilepsy phenotype-related genes were enriched in Reactome pathway of regulation of IGF transport and uptake by IGFBP in agreement with previous studies showing that increased IGF signaling exacerbates the AGS phenotype in the Fmr1 KO mice." (PMID 36506088, 2022).
Parkinsonism (25 papers, 2010 to 2026). Characteristic neurologic anomaly resulting from degeneration of dopamine-generating cells in the substantia nigra, a region of the midbrain, characterized clinically by shaking, rigidity, slowness of movement and difficulty with walking and gait. "This is the first report linking a point mutation in FMR1 to parkinsonism, demonstrating that the FMRP-P608L mutation impairs the D1R pathway by reducing its binding to GRK2." (PMID 40980401, 2025). "That differs from most of the data from the literature in which the FMR1 gray zone allele has been reported as risk factors for PD and parkinsonism in both females and males." (PMID 37906407, 2024). "Another study included 2,362 participants with a prevalence of 5.2% for carriers of the FMR1 gene GZ allele, and GZ alleles were associated with signs of Parkinsonism in men." (PMID 37583466, 2023). "They further supported that FMR1 gene GZ alleles are a significant risk factor for Parkinsonism in females." (PMID 37583466, 2023). "Therefore, FMR1 was proposed to be recognized as one of the exceptional genetic causes of parkinsonism with presynaptic dopaminergic loss and LBs." (PMID 40243562, 2025). "Genetic analysis of the FMR1 gene, suggested as one of the potential causes of parkinsonism, revealed a normal 27 CGG repeats in the 5’ UTR region; however, a missense mutation at the coding region (NM_002024.6: c.1877C>T, p.P626L) was identified in both the patient and his mother." (PMID 40980401, 2025). "IAs in the ATXN2 and ATXN1 genes may cause amyotrophic lateral sclerosis, and grey zone alleles of the FMR1 have been associated with parkinsonism." (PMID 38433266, 2024). "FXTAS was first described in 2001 with a clinical picture classically represented by intention tremor, cerebellar gait ataxia and parkinsonism, associated with hyperintensity of middle cerebellar peduncles at brain MRI and the premutation of the FMR1 gene (55–200 triplets)." (PMID 37906407, 2024). "Also, other neurodegenerative disorders are associated to FMR1 premutation, such as Parkinson disease or multiple sclerosis, pinpointing a crucial effect of FMRP mutations in common neuronal function and synaptic dysfunction." (PMID 34760921, 2021). "These neurons could be decreased in carriers as loss of FMR1 is associated with reduced numbers of dopaminergic neurons in the substantia nigra pars compacta as it has also been observed in Parkinson’s disease." (PMID 27570505, 2016). "In this study, we screened a missense mutation (NM_002024.6: c.1877C>T, p.P626L) in the coding region of the FMR1 gene from one male patient diagnosed with parkinsonism." (PMID 40980401, 2025). "This study aims to investigate the pathogenic role of a novel FMR1 missense variant from a parkinsonism patient without the typical CGG repeat expansion." (PMID 40980401, 2025). "Interestingly, the impact of the premutation, as observed in the FMR1 gene, extends beyond FXS and has been implicated in other neurodegenerative diseases, such as Parkinson’s disease (PD)." (PMID 38578387, 2024). "Previous studies supported the detection of FMR1 premutation in patients with PD or Parkinsonism." (PMID 37583466, 2023). "Clinical characteristics of patients with Parkinson’s disease harboring FMR1 CGG expansions." (PMID 37583466, 2023). "FMR1-premutation carriers may be considered neurotypical until later in adult life, when tremor, ataxia, and symptoms of parkinsonism become highly visible." (PMID 34686679, 2021). "Similar reductions in initial force production also have been reported in studies of Parkinson’s disease suggesting basal ganglia circuit functions may be affected during aging in FMR1 premutation carriers." (PMID 31632248, 2019). "Health outcomes in FXS may be associated with variations in the FMR1 gene, with related FMRP levels and epigenetic changes impacting clinical features, including intentional tremors, gait ataxia, parkinsonism, neuropathy, the autonomic nervous system, and reproduction." (PMID 40004478, 2025).
Parkinsonism (continued). "However, the actual prevalence of FXTAS might be higher given that no screening for FMR1 premutation was conducted in patients with other movement disorders, such as those with essential tremors or parkinsonism." (PMID 34498198, 2022). "Parkinsonism in FMR1-premutation carriers may be indistinguishable from PD23." (PMID 34686679, 2021).
Tremor (24 papers, 2008 to 2025). An unintentional, oscillating to-and-fro muscle movement about a joint axis. "As such, some participants in the PPD and FMR1 carriers (both of which develop tremor eventually) already show signs of this dysregulation of involuntary jitter in the walking patterns." (PMID 34686679, 2021). "In particular, numerous monogenic neurodegenerative, neuropathic and metabolic diseases manifest with tremor often accompanied by signs of other movement disorders, especially of a dystonic (e.g. ANO3, SGCE), ataxic (e.g. PPPP2R2B, ATX3, TBP) or parkinsonian (e.g. LRRK2, FMR1, ATX3) type." (PMID 39346806, 2024).
depression (21 papers, 2005 to 2023). "Further, higher levels of FMR1 mRNA are associated with an occurrence of neuropsychiatric conditions including depression and ADHD." (PMID 37120588, 2023). "Levels of mRNA are also linked with the age of depression onset in individuals with the FMR1 premutation, consistent with the hypothesis that mRNA toxicity builds over time, contributing to vulnerability." (PMID 28469730, 2017). "Of the linked FMR1 SNPs with most impressive association to depression, rs28900 may be part of a transcription factor binding site judging from ENCODE data, but no functional significance of rs25714 and rs25702 is apparent to us." (PMID 23521777, 2013). "As anticipated, the study revealed that higher ARs were linked to reduced FMR1 transcript levels for any given repeat length, and associated with enhanced performance, verbal, and full-scale IQ scores, as well as lower levels of depression, and a smaller number of medical conditions." (PMID 37759552, 2023). "Therefore, FMR1 is a candidate for an X-linked circadian gene causing susceptibility to depression." (PMID 23521777, 2013). "Supporting this notion is the fact that a genetic cross between Fmr1 KO and Tsc2+/- mice normalized long-term depression as well as performance in a contextual fear conditioning task." (PMID 29375310, 2017). "Considering the inconsistencies between samples and the likelihood that the significant three FMR1 SNPs might be linked to complex polymorphisms more functionally related to depression, large gene resequencing studies may be needed to clarify the import for depression of these circadian genes." (PMID 23521777, 2013). "In the GAIN depression study, data were available only for rs25714 among the FMR1 SNPs that were highly significant in the Sleep Clinic study." (PMID 23521777, 2013). "However, the samples were too small to ascertain this correlation, which needs larger samples to explore the relationship between depression and repeat size of FMR1 CGG repeat expansion in the future." (PMID 37583466, 2023). "For association with major depression, no FMR1 SNP was nominally significant, e.g., for rs25714, P=0.13, OR= -0.031." (PMID 23521777, 2013). "Further, meta-analysis of the 3 studies combined did not detect any significant FMR1 polymorphisms, and the GAIN GWAS study likewise failed to locate nominally significant association with major depression in the FMR1 region." (PMID 23521777, 2013). "The FMR1 5′ UTR triple repeat lengths in affected and unaffected GenRED sibs were approximately equal, apparently ruling out any frequent association of repeat expansion with early onset recurrent depression." (PMID 23521777, 2013). "Allelic instability affirms the complexity of FMR1 mutations and may relate to diverse phenotypes, including cognitive abilities and behavioral features observed in both FXS and PM disorders, specifically in female carriers of a PM allele with ADHD and depression." (PMID 37759552, 2023). "FMR1 mRNA expression was significantly higher in subjects with any psychiatric disorder diagnosis (P = 0.0017); specifically, in those with ADHD (P = 0.009), and with depression (P = 0.025)." (PMID 37120588, 2023). "Furthermore, FMR1 mRNA expression levels did not correlate with any of the clinical outcome measures included in this study (depression, number of medical conditions, BDS-2, and IQ)." (PMID 37443745, 2023). "FMR1 knockout mice that produce no FMRP show decreased neuropathic pain, protection from nociceptive sensitization or IL-6 induced allodynia, and protection from pain-induced emotional sequelae such as depression." (PMID 35126193, 2021).
developmental delay (20 papers, 2010 to 2025). "Overall results enable us to conclude that the developmental delay is the cumulative result of a methylated FMR1 full mutation on the active X-chromosome and the inactivation of the other homologue carrying the de novo 439 kb deletion." (PMID 29747568, 2018). "The most important clinical abnormality associated with defects of the FMR1 gene is global developmental delay/ID." (PMID 28420439, 2017). "Patients with Fragile X syndrome (FXS), caused by loss of function of the fragile X mental retardation 1 (Fmr1) gene, often exhibit many of the symptoms commonly associated with ASDs, such as developmental delays, communication impairments, and anxiety." (PMID 20300527, 2010). "Among 237 Thai boys with a developmental delay of unknown cause in Southern Asia, 16 (6.8%) were found to have a full FMR1 mutation, and four were reported to have a premutation." (PMID 37420260, 2023). "Clinically, the series reinforces guidance to include FMR1 analysis in genetic evaluations for unexplained developmental delay/ASD and to provide counseling when intermediate results are identified." (PMID 41346873, 2025). "Accordingly, professional guidance recommends genetic testing, including FMR1 analysis, during evaluation of children with unexplained developmental delay/ASD, particularly males." (PMID 41346873, 2025). "Bureau and colleagues demonstrated weak L4 to L2/3 synaptic strength in the global Fmr1 KO when measured at 2 weeks of age, but the difference was diminished at 3 weeks, suggestive of a developmental delay." (PMID 34617509, 2021). "Current guidance recommends genetic evaluation for children with unexplained developmental delay/ASD, including FMR1 analysis, particularly in males and when family history is suggestive." (PMID 41346873, 2025). "The reported deletions encompassing the FMR1 gene range from 35 kb to 3 Mb; they all have typical features of FXS involving ID from moderate to severe and developmental delay (DD) including motor and language development at various severities." (PMID 35646065, 2022). "Differences in findings may be related the younger age of the infant-sibling study, as well as differences in participants characteristics; Boys with full mutation of Fmr1 will all have developmental delays, whereas this is a risk but not a certainty for infants with ASD siblings." (PMID 33632320, 2021). "Given that astrocytes show developmental delays in FXS, we suggest that the expression levels of albumin and antithrombin III that we detected in Fmr1-KO hippocampal ACM may mirror the expression levels in ACM from the WT hippocampus at earlier time points." (PMID 27242437, 2016). "A significant developmental delay was seen in gap-ASSR responses in the FC, but not the AC, of female Fmr1 KO mice compared to WT female mice." (PMID 38720271, 2024).